LIF (LIF interleukin 6 family cytokine)
Diseases named in the same sentence as LIF in open-access papers (continued):
Sharing a sentence is not in itself a finding about the gene and the disease.
osteosarcoma (14 papers, 2017 to 2025). A usually aggressive malignant bone-forming mesenchymal neoplasm, predominantly affecting adolescents and young adults. "LIF was described as a super-enhancer-controlled regulator of stem cell-like properties in osteosarcoma." (PMID 40007535, 2025). "Another example of the CRC’ critical component in osteosarcoma is LIF being an essential factor under the control of osteosarcoma-specific SE." (PMID 38542080, 2024). "Epigenetic profiling of osteosarcoma cells identified leukemia inhibitory factor (LIF) as an essential factor controlled by super enhancers." (PMID 35563709, 2022). "Choriocarcinoma cell and osteosarcoma cell line and mouse models have shown cancer cell invasiveness is potentially due to LIF-induced STAT3 activation." (PMID 35204717, 2022). "Within osteosarcomas, LIF overexpression significantly correlates with advanced stage, larger tumor size, and decreased survival." (PMID 35204717, 2022). "The expression of LIF was significantly higher in osteosarcoma cell lines and tumors and its expression levels were positively correlated to the stem cell core fators SOX2 and Nanog." (PMID 34198693, 2021). "For example, osteosarcoma-specific SEs promote tumor stemness by directly activating the expression of leukemia-inhibitory factor (LIF)." (PMID 34011395, 2021). "Mechanistically, they found SEs function as an activator of the NOTCH1 pathway through regulating the LIF/STAT3 pathway in promoting the progression of osteosarcoma." (PMID 32714929, 2020). "Moreover, the treatment of osteosarcoma cells with recombinant LIF protein improved sphere-formation, augmented their invasiveness and increased the expression of CSC-related genes, such as CD133, SOX2, Nanog and OCT4." (PMID 34198693, 2021). "Finally, the leukemia-inhibitory factor (LIF) has been recently reported as an essential factor under the control of super-enhancers that are specific to osteosarcoma." (PMID 34198693, 2021). "LIF promotes the stem cell properties of osteosarcoma through the NOTCH1 signaling pathway and enhances the growth and invasion of osteosarcoma by activating STAT3 signaling, while blocking STAT3 signaling can inhibit the development of osteosarcoma." (PMID 35740622, 2022). "Therefore, the UTX inhibitor GSK-J4 is able to reduce the endogenous levels of LIF in osteosarcoma cells through in combination of epigenetic signals that affect NOTCH1 signaling, including an increase of H3K27me3 and a decrease in H3K27ac at LIF gene locus." (PMID 34198693, 2021). "LIF activation of NOTCH1 signaling by H3K27me3 demethylation through the Ubiquitously Transcribed Tetratricopeptide Repeat on chromosome X (UTX) histone demethylase correlated with “stemness” related genes, sphere formation, self-renewal and metastasis in osteosarcoma." (PMID 35563709, 2022).
retinal degeneration (14 papers, 2009 to 2023). Degeneration of the retina. "Such is the case for leukemia inhibitory factor (LIF), which is produced by a subset of MG cells and was dependent on p38 in a light-induced model of retinal degeneration." (PMID 36831285, 2023). "In a mouse model of light-induced retinal degeneration, intravitreal delivery of LIF improved PR survival and retinal function by activating STAT3 in Müller glia and PR." (PMID 36389729, 2022). "In the animal models of retinal degeneration, photoreceptor cell death strongly induces the expression of LIF in a subset of Müller glial cells in the INL of the retina." (PMID 35269741, 2022). "Many of the factors involved in this “dialogue” have been identified; MGC release several molecules, such as FGF, GDNF, DHA, and LIF, that rescue PHRs in different models of retinal degeneration." (PMID 31402853, 2019). "Given the preponderance of data showing that induced expression of LIF can delay retinal degenerations, this study now links that activation of PRRs to this induced protective response." (PMID 29904087, 2018). "LIF signaling during retinal degeneration is thought to act through the JAK/STAT pathway including activation of Janus activated kinase 2 (JAK2), JAK3 and signal transducers and activators of transcription 3 (STAT3)." (PMID 23372671, 2013). "It is of significance that LIF acts as a neuroprotective not only in the light damage paradigm but also in models of inherited retinal degeneration." (PMID 19693290, 2009). "This expression, however, depends on LIF in a model of inherited retinal degeneration as well as in the light damage model." (PMID 19693290, 2009). "In summary, we show that lack of LIF signaling leads to increased photoreceptor death in the light-induced model (this work) and in a model of inherited retinal degeneration." (PMID 19693290, 2009). "We show that the presence of LIF indeed reduced the severity of degeneration also in the light damage model and that this protection uses a similar signaling system as detected earlier in the inherited model of retinal degeneration." (PMID 19693290, 2009). "To investigate whether such a LIF-controlled survival pathway might be commonly induced upon photoreceptor injury independently of the nature of the toxic stimulus, we analyzed the role of LIF during light-induced retinal degeneration." (PMID 19693290, 2009). "The highest SF3/SF1 proteins are known to have antioxidant effects, including NGF, BDNF, PEDF, and LIF, suggesting that SF3 would have greater antioxidant effects and efficacy in models of retinal degeneration." (PMID 37443724, 2023). "CNTF therapy enhances the protective properties of Müller glia through LIF/gp130/STAT3 signaling, thereby preventing retinal degeneration." (PMID 36389729, 2022). "Intravitreal delivery of LIF, CNTF, brain-derived neurotrophic factor (BDNF), or FGF2 promotes survival of photoreceptors after light damage or inherited retinal degeneration, and protects retinal ganglion cells after ischemic injury." (PMID 22701694, 2012). "Genetic models of retinal degeneration show increased FGF2 and leukemia inhibitory factor (LIF) expression." (PMID 22701694, 2012). "On the other hand, in the absence of LIF, Müller glial cells remain quiescent and retinal degeneration is enormously accelerated." (PMID 35269741, 2022). "We observed that UPA is capable of strongly inhibiting the JAK/STAT pathway in LIF induced rMC-1 cells, an indication to us that this drug and inhibition of the JAK/STAT pathway could be beneficial in the treatment of RP and other retinal degenerations." (PMID 34439829, 2021). "Since it has been shown in other systems that CDC42 can participate in the endothelin and LIF signaling pathways, we tested whether the ablation of CDC42 in rods might affect the molecular response during retinal degeneration." (PMID 22128240, 2011).
retinal degeneration (continued). "In addition to regulation by a number of growth factors, including the neuroprotective factors LIF and PEDF, small molecule activators of UCP2 have been found to reduce mitochondrial ROS production and protect against cell death both in culture and animal models of retinal degeneration." (PMID 35628482, 2022).
Stroke (12 papers, 2014 to 2025). Sudden impairment of blood flow to a part of the brain due to occlusion or rupture of an artery to the brain. "Therefore, LIF may indirectly reduce the neuroinflammation-associated damage during stroke by increasing the population of anti-inflammatory macrophages/microglia." (PMID 30322390, 2018). "Our results align with these findings and provide further evidence that LIF treatment can positively influence in vivo mitochondrial respiration in MCAO stroke models, suggesting LIF’s role in protecting against ischemia-induced mitochondrial function damage." (PMID 40427631, 2025). "Our findings suggest that LIF/LIFR interactions mediate beneficial effects of CD8+ TRLs early after stroke." (PMID 35912857, 2022). "We administered a LIF treatment on half of the rats based on previous work suggesting that LIF is an anti-inflammatory that regulates the immune/inflammatory response to stroke." (PMID 36825211, 2022). "This manuscript explores how LIF treatment modulates the splenic inflammatory response after stroke in an age-dependent and sex-dependent manner." (PMID 33376583, 2020). "Previously, this lab demonstrated that LIF prevents the stroke-mediated increase in splenic CXCL10 at 72 h after stroke." (PMID 33376583, 2020). "Although this study primarily examined the effects of LIF in the spleen and brain after stroke, it is entirely possible that LIF signaling is indirectly modulating the post-stroke immune response through its actions in other tissues." (PMID 30322390, 2018). "Preliminary results show that LIF exhibits potent anti-inflammatory signaling in the splenocytes of aged female rats after stroke." (PMID 30322390, 2018). "LIFR is degraded after prolonged stimulation with LIF in many cell types, which indicates that the splenocytes were responsive to peripherally administered LIF after stroke." (PMID 30322390, 2018). "Previously, we showed that LIF reduces tissue damage and improves function recovery after stroke through the Akt-dependent upregulation of antioxidant enzymes in neurons and oligodendrocytes." (PMID 30322390, 2018). "By counteracting the IFNγ-mediated increase in splenic IP-10, LIF treatment would decrease the number of pro-inflammatory immune cells migrating to the brain after stroke." (PMID 30322390, 2018). "Due to its effects on the hypothalamus-pituitary-adrenal axis, it is possible that LIF administration is influencing the post-stroke immune response through the regulation of cortisol release." (PMID 30322390, 2018). "This laboratory is currently performing studies to determine the neuroprotective efficacy and anti-inflammatory action of LIF in aged (18 month) male and female rats after stroke." (PMID 30322390, 2018). "In vitro experiments using cultured oligodendrocytes and Prdx4 antibodies confirmed that the ability of LIF to reduce oxidative damage to white matter during stroke is primarily dependent upon its upregulation of Prdx4 through PI3K/Akt signaling." (PMID 26746670, 2017). "The CD133+ ependymal cells’ inability to self-renew makes them distinctly different from the AdpNSCs, which are able to self-renew in vivo, as illustrated by their expansion in number after LIF infusion and stroke." (PMID 24936468, 2014). "LIF treatment is efficacious in reducing the splenic inflammatory response to stroke." (PMID 36825211, 2022). "Mouse models of myocardial and cerebral infarction show an important role of LIF in neovascularization of myocardium after the infarct, as well as neuroprotective actions after a stroke, the actions of LIF within these ischemic pathologies reiterates the induction of LIF by hypoxia." (PMID 35204717, 2022). "Additionally our previous studies found that leukemia inhibitory factor (LIF) inhibits the peripheral immune response to stroke." (PMID 36825211, 2022).
Stroke (continued). "Since levels of LIFR in the brains of aged female rats were lower than those of aged male rats after stroke, the partial recovery observed in aged female rats after LIF treatment may be attributed to stronger anti-inflammatory activity." (PMID 33376583, 2020). "The goal of this study was to determine whether leukemia inhibitory factor (LIF) promotes anti-inflammatory activity after stroke in a sex-dependent manner." (PMID 33376583, 2020). "Leukemia inhibitory factor (LIF), a cytokine in the IL-6 family, has shown efficacy in promoting cellular survival and countering peripheral inflammation when administered intravenously after permanent stroke." (PMID 33376583, 2020). "However, soluble factors released from HUCB cells, which include LIF, also promote anti-inflammatory signaling after stroke." (PMID 30322390, 2018). "Through this study and previously published manuscripts, this lab has demonstrated that LIF treatment after stroke promotes neuroprotection and recovery through two distinct mechanisms: Akt-dependent upregulation of antioxidant enzymes and modulation of the IL-12 p40/IFNγ/IP-10 signaling pathway." (PMID 30322390, 2018). "We concluded that the protective effects of LIF occur during early period following stroke." (PMID 29896414, 2018). "The purpose of this study is to determine whether LIF alters the post-stroke splenic response by changing the phenotype of macrophages/microglia from a pro-inflammatory to an anti-inflammatory phenotype." (PMID 30322390, 2018). "The goal of this study was to determine whether LIF treatment modulates the peripheral immune response after stroke." (PMID 30322390, 2018). "This lab tested the hypothesis that LIF increases neuronal survival after stroke by upregulating SOD enzyme expression and activity." (PMID 26746670, 2017). "As a result, LIF may reduce neurodegeneration triggered by the release of inflammatory splenocytes after stroke." (PMID 26746670, 2017). "The goal of this study was to determine whether LIF protects neurons during stroke by upregulating superoxide dismutase 3 (SOD3)." (PMID 26746670, 2017). "The ability of LIF to activate protective pathways and reduce neural cell damage in several animal models of disease makes it a prime candidate for targeting delayed neuronal death after stroke." (PMID 26746670, 2017). "Many types of injuries to the nervous system are accompanied by a rapid and transient increase in LIF expression; hence, we asked whether increased LIF signaling played a role in the activation of AdpNSCs in our stroke model." (PMID 24936468, 2014). "The goal of this study was to determine whether LIF protects ischemia-induced altered mitochondrial bioenergetics in reproductively senescent aged rats of both sexes (≥18 months old), approximately equivalent to the average age of human stroke patients." (PMID 40427631, 2025). "Salivary basic FGF, HGF, IL-3 and LIF could serve as potential biomarkers for stroke." (PMID 40221607, 2025). "Therefore, we sought to determine the effect of LIF on the microbiome following stroke." (PMID 36825211, 2022). "Therefore, examining expression of LIFR among leukocyte populations might provide further insight into how LIF promotes anti-inflammatory signaling in splenocytes and peripheral blood leukocyte after stroke." (PMID 30322390, 2018). "Previously, LIF, a neuroprotective and anti-inflammatory cytokine, was shown to decrease neurodegeneration and increase survival after a MCAO stroke model surgery in rats." (PMID 40427631, 2025). "Previously, this laboratory demonstrated that LIF treatment significantly reduced splenic IFN-gamma and prevented the upregulation of CXCL10 after stroke." (PMID 33376583, 2020). "Although LIF treatment prevented the increase in splenic CXCL10 in young male rats, we did not observe a significant change in splenic CXCL10 levels after a stroke or LIF treatment among aged rats of either sex." (PMID 33376583, 2020).
Stroke (continued). "Although CD3 is expressed by all T cells, this reduction coupled with the downregulation in IFNγ production suggest that LIF prevents the maturation of CD8+ cytotoxic T cells, which are the major producer of IFNγ after stroke." (PMID 30322390, 2018). "In the unstimulated saliva of stroke patients, we demonstrated significantly higher levels of chemotactic factors (CTACK/CCL27, IL-8/CXCL8, MIG/CXCL9, MIF) and growth factors (basic FGF, G-CSF, HGF, LIF, VEGF) compared to controls." (PMID 40221607, 2025). "This study also found that stroke-induced motor dysfunctions were attenuated by LIF-treatments in male, but not female, rats." (PMID 40427631, 2025). "A previous study by this laboratory showed that administration of LIF at 24, 48, and 72 h after stroke did not significantly decrease edema or cytotoxicity, although there was a trend towards decreased brain damage among female LIF-treated rats." (PMID 33376583, 2020). "Also, LIF treatment promotes anti-inflammatory signaling by decreasing splenic levels of IFNγ and preventing the upregulation of CXCL10 that occurs after stroke." (PMID 33376583, 2020). "Although this laboratory has previously shown that the decrease in spleen size is observed as early as 24 h after stroke, this laboratory did not observe any LIF-mediated alteration in LIFR expression or spleen size prior to the 72-h time point." (PMID 30322390, 2018). "Leukemia inhibitory factor (LIF) is a cytokine in the IL-6 family that promotes survival of neurons and glia in several animal models of neurodegenerative disease, such as amyotrophic lateral sclerosis, multiple sclerosis, spinal cord injury, and stroke." (PMID 30322390, 2018). "Although LIF is released by several cell types during brain injury, its potential as a stroke therapeutic has not yet been determined." (PMID 26746670, 2017). "However, this study shows that the presence of LIF has no influence on the changes in the microbiome that occurs after stroke." (PMID 36825211, 2022).